ZYX (zyxin)
Diseases named in the same sentence as ZYX in open-access papers (continued):
Sharing a sentence is not in itself a finding about the gene and the disease.
tumor (31 papers, 2007 to 2026). "The relationship between miR-21, miR-17, and miR-155 and the novel MDR markers such as SEH1L, TUBA4A, and ZYX was revealed, thereby expanding the current understanding of the molecular mechanisms underlying tumor cell resistance to chemotherapy." (PMID 41463125, 2025). "This study shows that innate immune signaling via cGAS-STING or RLR-MAVS regulates tumor-associated macrophage tissue residency through activation of the TBK1-Zyxin axis." (PMID 39304793, 2024). "According to previous studies and the result of our study, it can be concluded that ZYX has both oncogenic and tumor‐suppressant effects, and its function is associated with the organ involved and its mutual protein partners." (PMID 39100715, 2024). "Based on IHC, Mantel–Cox tests showed that higher levels of cytoplasmic ZYX in tumor cells were associated with longer overall survival (OS)." (PMID 35740950, 2022). "A total of 17 proteins were verified as potent tumor markers, especially, a novel plasma-based biomarker, zyxin (ZYX) was identified as a potential early diagnostic marker for NSCLC." (PMID 28615068, 2017). "During mitosis, a fraction of zyxin becomes associated with the tumour suppressor h-warts at the mitotic apparatus." (PMID 17211471, 2007). "Zyxin is a phosphoprotein that has been implicated in modulation of multiple cellular functions, including cell growth, cell motility, cell adhesion, stress fiber formation, and tumor growth." (PMID 23267329, 2012). "In terms of tumor suppression, zyxin is known to bind to Cell Cycle and Apoptosis Regulatory Protein 1 (CARP-1)." (PMID 38712343, 2024). "A STING-dependent adhesion and residency of TAMs in the tumor microenvironment was confirmed through genetic deletions of Zyxin, STING, and IRF3." (PMID 39304793, 2024). "Noticeably, cGAMP promoted the aggregation of F4/80+ cells at the edge of B16-F10 tumors (Fig. EV6B), while Zyxin deletion inhibited tumor growth at a level comparable to cGAS-STING activation." (PMID 39304793, 2024). "Can STING-TBK1-Zyxin signaling detain TAMs in tumor microenvironments and thus suppress antitumor immunity?" (PMID 39304793, 2024). "Innate immune sensing pathways activate the TBK1 kinase for phosphorylation of the actin dynamics regulator Zyxin to trap macrophages in the tumor." (PMID 39304793, 2024). "Based on our observation, expression of the ZYX gene in tumor tissue was reduced compared to matched margin tissue." (PMID 39100715, 2024). "The data showed that expression of the ZYX gene in tumor tissues significantly decreased (p = 0.0274) compared to matched margin tissues." (PMID 39100715, 2024). "Experimental evidence shows that Zyxin depletion leads to decreased cell proliferation rates and reduces tumor volume and weight." (PMID 38712343, 2024). "The expression of the ZYX gene in tumor tissues significantly decreased (p = 0.0274) compared to matched margin tissues." (PMID 39100715, 2024). "Aberrant zyxin expression is closely correlated with tumor cell activity and cardiac function in both tumorigenesis and cardiovascular diseases." (PMID 38712343, 2024).
tumor (continued). "We used a mouse xenograft model to assess the impact of zyxin overexpression on tumor growth in vivo." (PMID 37667739, 2023). "Taken together, ZYX promoted the growth of HCC xenograft in vivo by enhancing proliferation of the tumor cells." (PMID 37547758, 2023). "To explore the effect of zyxin on tumor stemness, we overexpressed zyxin in N87 and MKN45 cells and analyzed expression levels of CD44 and OCT4." (PMID 37667739, 2023). "The same relationships were observed when tumor size (pT) was compared with the levels of cytoplasmic ZYX in lung SCC and lung AC cells." (PMID 35740950, 2022). "IHC reactions showed the presence of ZYX in the cytoplasm, cell membrane, and in the cell nucleus of tumor cells and NMLT cells." (PMID 35740950, 2022). "RT-qPCR results obtained using laser microdissected sections confirmed lower ZYX mRNA expression in tumor cells compared with normal cells." (PMID 35740950, 2022). "Further analyses showed that the levels of cytoplasmic ZYX in NSCLC cells decreased with increasing tumor size (pT)." (PMID 35740950, 2022). "In contrast, zyxin attenuated tumor growth, reconstituted FA organization with the actin cytoskeleton and decreased cell motility in a Ewing sarcoma model." (PMID 34867475, 2021). "In fact, harmine-treated tumor cells recovered their actin cytoskeleton with the occurrence of stress fibers (third and fourth columns) and zyxin-rich focal complexes." (PMID 32397195, 2020). "Mice bearing Zyxin-silenced cells showed average 3.9-fold and 3.2-fold decrease in tumour weight and volume compared with scramble group, respectively." (PMID 27030211, 2016). "Immunoblotting analysis of the implanted tumour tissues revealed increased Lats2 and p-Yap levels in Zyxin-knockdown tumours." (PMID 27030211, 2016). "Expression of the MRTF-SRF transcription pathway-linked target genes, such as caldesmon, tropomyosin, vinculin, and zyxin, are reduced in certain tumor cells, and their forced re-expression reverses many malignant phenotypes of tumor cells." (PMID 27708220, 2016). "Zyxin gene transfer into EWS-FLI1-transformed fibroblasts leads to inhibition of anchorage independent tumor growth, indicating that zyxin has tumor suppressor activity in these cells." (PMID 18419822, 2008). "Beyond zyxin’s impact on endothelial cell exocytosis, it may also regulate mechanosensitive gene expression and enhance the adhesion and migration of tumour cells." (PMID 41596291, 2026). "Furthermore, the immunofluorescence assay of tumor tissues demonstrated a significant decrease in expression of ZYX after treatment with sh‐ABHD11‐AS1 lentivirus (n = 3)." (PMID 39703167, 2025). "Though insignificant, clodronate liposomes somewhat improved tumor growth in Zyxin KO mice." (PMID 39304793, 2024). "Overexpression of zyxin in MKN45 cells inhibited tumor growth in nude mice." (PMID 37667739, 2023).
tumor (continued). "Among the exclusively detectable Exo-prots in the NB patients, we identified the nucleolar protein NPM1 as being overexpressed in hematologic and solid tumors and ZYX involved in focal adhesion and in the regulation of actin cytoskeleton with a role in cell motility and tumor invasion." (PMID 37947594, 2023). "In contrast, overexpression of ZYX accelerated tumor growth in vivo." (PMID 37547758, 2023). "It was suggested that impaired interaction between β-catenin and moesin, E-cadherin, or ZYX could impair the formation of cell adhesion junctions/adherens junctions and thus promote tumor progression." (PMID 35740950, 2022). "However, nuclear ZYX levels were increased in tumor cells compared with control tissue (p < 0.0001)." (PMID 35740950, 2022). "Real-time PCR performed on laser capture microdissected sections showed lower ZYX mRNA expression in tumor cells of the whole NSCLC group (p < 0.0001), of the SCC subtype (p < 0.0001), and of the AC subtype (p < 0.0001) compared with non-malignant lung cells (NMLC)." (PMID 35740950, 2022). "Cytoplasmic expression of ZYX in tumor cells was found in 207 (51.88%) NSCLC cases." (PMID 35740950, 2022). "Zyxin could affect tumour haemorrhaging and growth because it has been shown to regulate the exocytosis of endothelial Weibel–Palade body (WPB) and the secretion of von Willebrand factor (vWF)." (PMID 33573141, 2021). "Cells with the highest levels of zyxin recover a fibroblastic morphology, stress fibers, focal adhesions and cell–cell contacts; they exhibit reduced intrinsic motility, anchorage-independent growth and decreased tumor growth in nude mice." (PMID 32397195, 2020). "The xenograft experiments further validate our notion that Zyxin ablation could indeed deactivate Hippo signalling in planting tumours." (PMID 27030211, 2016). "By supporting the involvement of the microfilament network in tumor cell behavior, several actin-binding proteins, including Zyxin, a potential regulator of actin polymerization, may play a role in oncogenesis." (PMID 19874631, 2009). "Zyxin may also influence other immune and tumor cells, which warrants further investigation." (PMID 39304793, 2024). "Thus, it can be suggested that in the case of NSCLC, ZYX may regulate actin polymerization or may function as a transport molecule for other molecules into the nucleus, thus enabling tumor progression." (PMID 35740950, 2022). "Additionally, zyxin may be used as a phenotypic marker for tumor cells with a high propensity for invasion." (PMID 35501542, 2022). "Thus, the decrease in ZYX expression, which was observed in our study, may increase the survival of tumor cells and thus promote tumor progression." (PMID 35740950, 2022). "Interestingly, zyxin is upregulated upon shear stress and translocates from cell–matrix adhesions to the nucleus where it affects gene expression, indicating alternative ways to influence tumour development." (PMID 33573141, 2021). "Thus, the tumour suppressor versus oncogenic roles of BPAG1e could rely upon Zyxin functions and interacting partners in distinct epithelia." (PMID 31882643, 2019). "It was found that high expression of ZYX, GJA1, and TUBA4A indeed correlated well with low sensitivity of tumor cells to DOX and, moreover, to another anticancer drugs, such as vincristine, topotecan, panobinostat, and cytarabine." (PMID 41153808, 2025). "To address this issue, we calculated hazard ratio (HR) values for SEH1L, TUBA4A, TCF3, ZYX, and GJA1, both individually and in combination, using tumor data from The Cancer Genome Atlas (TCGA)." (PMID 41153808, 2025). "Thus, ZYX might be necessary in tumor suppressor function of myopodin." (PMID 39100715, 2024). "Therefore, based on our results, ZYX may have a tumor suppressor function in BC." (PMID 39100715, 2024).
tumor (continued). "Among the exclusively detectable Exo-prots in the NB patients, we identified the MYC target nucleophosmin (NPM1) and the actin interacting protein zyxin (ZYX), known for their role in tumor proliferation and invasiveness." (PMID 37947594, 2023). "In our study, we demonstrated that cytoplasmic ZYX levels in all NSCLC cases and in the SCC subtype (which was analyzed separately) decreased with increasing tumor size." (PMID 35740950, 2022). "Materials and Methods: The expression of ZYX was assessed in NSCLC cases and in cell lines representing this tumor type." (PMID 35740950, 2022). "Apart from WDR1, several other oncoproteins and tumour suppressors, such as LDHA, CLIC1, ARPC5, ZYX, RCN1, FHIT and CFTR, were identified in this study." (PMID 32601462, 2020). "Consistent with observations in global Zyxin KO, we observed a marked inhibition of tumor growth in Zyxin KO mice only in the control group rather than in groups with macrophage depletion." (PMID 39304793, 2024). "The decreased F4/80+ macrophages and reduced tumor growth in Zyxin−/−;Irf3−/− mice suggested that the enhanced antitumor immunity observed upon Zyxin depletion was at least partially independent of the TBK1-IRF3 axis." (PMID 39304793, 2024). "Tumor growth curves and weights were comparable between WT and Zyxin KO B16-F10 tumors, further supporting that Zyxin depletion does not impact tumor growth but probably influences antitumor immunity." (PMID 39304793, 2024). "The hypothesis of a suppressor role of ZYX in NSCLC development may also be supported by the results of the analysis of the relationship between the level of this protein and tumor size." (PMID 35740950, 2022). "In our study, the levels of nuclear ZYX in NSCLC cases were significantly higher compared with normal lung tissue, which may indicate that ZYX is translocated to the nucleus to induce apoptosis as a defense mechanism against further tumor progression." (PMID 35740950, 2022). "We show that LIM domain protein Zyxin, as a scaffold protein, in response to hypoxia and TGF-β stimuli, forms a ternary complex with Siah2 and Lats2, thus stabilizes their interaction, and facilitates deactivation of the Hippo signalling, thereby promoting tumour progression." (PMID 27030211, 2016). "In reverse, tumour cells, that are overexpressing LASP-1, could functionally inhibit zyxin from shuttling into the nucleus and acting as a tumour suppressor through increased recruiting of zyxin to focal contacts by LASP-1." (PMID 17211471, 2007). "Zyxin gene transfer into EWS-FLI1-transformed fibroblasts elicits reconstitution of zyxin-rich focal adhesions and leads to decreased cell motility and inhibition of anchorage independent tumour growth, indicating that zyxin has tumour suppressor activity in these cells." (PMID 17211471, 2007). "However, harmine induces the reversion of the tumor phenotype of EWS-Fli1-transformed cells without recovering the expression level of zyxin, suggesting that this molecule acts through a mechanism that is different from that observed in the case of re-expression of zyxin in these cells." (PMID 32397195, 2020).
infection (5 papers, 2017 to 2025). The state of being infected such as from the introduction of a foreign agent such as serum, vaccine, antigenic substance or organism. "CRISPR-Cas9 targeting of zyxin produced one of the strongest changes in HSV-1 early infection in our screen." (PMID 38953638, 2024). "Collectively, these findings support a role for zyxin in restricting alphaherpesvirus infection at an initial step of infection." (PMID 38953638, 2024). "Several other putative host factors were novel, including zyxin, which was identified as an antagonist of early infection." (PMID 38953638, 2024). "Intriguingly, human papillomavirus (HPV) has been demonstrated to induce the nuclear accumulation of zyxin during infection, through the action of its E6 protein." (PMID 33572997, 2021). "During infection, we observed that even small, likely nascent adhesions present at the leading edge of the cell contained zyxin." (PMID 32843479, 2020). "According to the proteomics data, zyxin, a zinc-binding phosphoprotein, was significantly decreased following WT and Mut-2 infection." (PMID 29207503, 2017). "Since hMPV infection is restricted in the airway tract, it is unlikely for zyxin to carry out such a function in the context of hMPV infection." (PMID 29207503, 2017). "Zyxin knockout cells were hyper-permissive to infection and could be rescued with even modest expression of GFP-zyxin." (PMID 38953638, 2024). "Importantly, the striking nuclear accumulation of zyxin during infection had the downstream consequence of enabling zyxin’s function as a transcriptional activator." (PMID 33572997, 2021). "It is possible additional chlamydial factors are required to fully alter the maturation state of host cell adhesions or that changes in intracellular tension during infection may play a role, as zyxin has been shown to be a mechanosensitive protein." (PMID 32843479, 2020). "This is consistent with zyxin restricting an early step of infection (e.g., by slowing genome delivery) but not subsequently impairing virus production thereafter." (PMID 38953638, 2024). "The most significant impact of zyxin knockout was observed in plaque size, which unlike the reporter gene expression assays occurs over multiple rounds of infection." (PMID 38953638, 2024). "Additionally, the size of plaques formed following infection with members of each viral family was increased in the absence of zyxin." (PMID 41277845, 2025). "On the other hand, six targets produced positive Z-scores (>1.96) that indicated increased infection upon CRISPR targeting: RANBP2-like and GRIP domain containing 2 and 4 (RGPD2 and RGPD4), trinucleotide repeat containing adaptor 6B (TNRC6B), FAM21C, KIA00196 (aka, strumpellin), and zyxin." (PMID 38953638, 2024). "Alternatively, cell junctions and cortical actin are barriers to infection that may be disrupted in the absence of zyxin." (PMID 38953638, 2024).
cardiovascular diseases (3 papers, 2021 to 2026). "More research and experimental evidence are needed to further elucidate the exact role and mechanisms of zyxin in cardiovascular diseases." (PMID 38712343, 2024). "Zyxin’s relationship with cardiovascular diseases requires further comprehensive research for a thorough understanding." (PMID 38712343, 2024). "Although there have been some studies regarding the relationship between zyxin and cardiovascular diseases, these studies are primarily limited to animal models." (PMID 38712343, 2024). "This suggests that Zyxin could have potential implications in the treatment of cardiovascular diseases, emerging as a novel area for regulating cardiomyocyte function." (PMID 38712343, 2024). "Some studies suggest that zyxin may play a role in the occurrence and development of cardiovascular diseases." (PMID 38712343, 2024).
bacterial infection (2 papers, 2017 to 2019). "In our case, LIM domain containing proteins such as migfilin and zyxin did not colocalize with the clustered chimeric receptors upon bacterial infection, further supporting the idea that OPTIC mimicks the initial, force-independent events after integrin activation." (PMID 30952878, 2019).
myopathy (1 paper, 2025). A disease of the muscle in which the muscle fibers do not function properly. "Other proteins of cytoskeleton such as Myosin, Tubulin, Myotilin, Vimentin, Zyxin, Nexilin, and Troponin were found to be differentially expressed in GNE myopathy muscle biopsy samples." (PMID 41339784, 2025).
neurodegenerative disease (1 paper, 2024). A disorder of the central nervous system characterized by gradual and progressive loss of neural tissue and neurologic function. "In neurodegenerative diseases like Alzheimer’s, the aberrant expression and functional disruption of Zyxin may be linked to the initiation and progression of the disease." (PMID 38712343, 2024). "In the case of neurodegenerative diseases such as Alzheimer’s disease (AD), the abnormal expression and dysfunction of zyxin may be associated with the onset and progression of the disease." (PMID 38712343, 2024).